SNORD3A (small nucleolar RNA, C/D box 3A)
Synonyms: U3; RNU3
Gene: Small nucleolar RNA gene on chromosome 17 (19,188,016 to 19,188,714, forward strand). Ensembl gene ENSG00000263934.
Gene Ontology:
Biological process: RNA processing
Cellular component: nucleolus
Diseases named in the same sentence as SNORD3A in open-access papers:
SNORD3A is named in the same sentence as 21 diseases in open-access papers, as found by Europe PMC text mining. Sharing a sentence is not in itself a finding about the gene and the disease. The quoted sentences say what the papers report.
breast carcinoma (6 papers, 2020 to 2024). "Given that SNORD3A expression was downregulated in breast cancer cells and tissues, we next explored the mechanisms underlying SNORD3A downregulation." (PMID 32382150, 2020). "The functional importance of SNORD118 and SNORD3A in tumorigenesis has also been reported in lung cancer and breast cancer cells." (PMID 38942785, 2024). "In breast cancer, SNORD3A sensitizes cells to chemotherapy by acting as a miRNA sponge for miR-185-5p, leading to uridine monophosphate synthetase protein upregulation." (PMID 37215987, 2023). "We also examined the subcellular location of SNORD3A and found that SNORD3A resides in both the nucleus and the cytoplasm of breast cancer cells." (PMID 32382150, 2020). "Collectively, these data suggested that miR-185-5p is highly expressed in breast cancer and that SNORD3A acts as a sponge to miR-185-5p to promote UMPS expression in breast cancer cells." (PMID 32382150, 2020). "Bioinformatics analysis combined with experimental validation indicated that Meis1 was downregulated in breast cancer and positively regulated SNORD3A expression at the transcriptional level." (PMID 32382150, 2020). "In breast cancer tissues, SNORD3A level positively correlates with Meis1 and UMPS protein levels, whereas miR-185-5p level negatively correlates with UMPS protein level." (PMID 32382150, 2020). "Correlation analysis indicated that Meis1 level was positively correlated with SNORD3A level in breast cancer tissues." (PMID 32382150, 2020). "Given that SNORD3A enhanced chemosensitivity to 5-FU depending on UMPS and that SNORD3A acts as miR-185-5p sponge to promote UMPS expression in breast cancer cells, we examined the involvement of miR-185-5p in SNORD3A-mediated chemosensitization to 5-FU." (PMID 32382150, 2020). "Ectopic miR-185-5p expression overcame the chemosensitization induced by SNORD3A in in vitro and in vivo models, indicating that SNORD3A acts as a ceRNA for miR-185-5p in breast cancer cells." (PMID 32382150, 2020). "Our findings indicate that Meis1-regulated SNORD3A specifically sensitizes breast cancer cells to 5-FU via enhancing UMPS expression." (PMID 32382150, 2020). "SNORD3A enhances UMPS expression by sponging miR-185-5p to specifically promote chemosensitivity to 5-FU in breast cancer." (PMID 32382150, 2020). "Together these results suggested that Meis1 transcriptionally regulates SNORD3A expression in breast cancer cells." (PMID 32382150, 2020). "Together these data demonstrated the clinical significance of SNORD3A-mediated signaling in breast cancer patients." (PMID 32382150, 2020). "To further define the role of SNORD3A and verify its correlation with the newly identified upstream regulator and downstream effectors in breast cancer clinical samples, we first examined SNORD3A and miR-185-5p levels via ISH in breast cancer tissues (N = 72)." (PMID 32382150, 2020). "Both plate colony-formation and soft agar colony-formation assays also confirmed that SNORD3A overexpression specifically promoted the chemosensitivity of breast cancer cells to 5-FU." (PMID 32382150, 2020). "We confirmed the downregulation of SNORD3A in breast cancer cells and tissues and demonstrated a novel mechanism by which SNORD3A regulates chemosensitivity to 5-fluorouracil (5-FU) in breast cancer." (PMID 32382150, 2020). "In contrast to our data, in breast cancer, SNORD3A overexpression chemosensitizes cells to 5-fluorouracil (5-FU), by negatively regulating miR-185-5p." (PMID 32599901, 2020). "Together these in vitro and in vivo results indicated that miR-185-5p is involved in SNORD3A-mediated sensitization to 5-FU in breast cancer cells." (PMID 32382150, 2020). "The results demonstrated that SNORD3A expression was downregulated in breast cancer cells compared with MCF10A cells." (PMID 32382150, 2020). "SNORD3A is downregulated in breast cancer resulting from Meis1 downregulation." (PMID 32382150, 2020).
breast carcinoma (continued). "Together, these data suggest that SNORD3A may promote 5-FU sensitivity by activating UMPS expression in breast cancer cells." (PMID 32382150, 2020). "Moreover, Meis1 overexpression transcriptionally promotes SNORD3A expression, and Meis1 is downregulated in breast cancer cells and tissues." (PMID 32382150, 2020). "We also explored preliminary the mechanism for SNORD3A downregulation in breast cancer." (PMID 32382150, 2020). "Our findings provide insight into the SNORD3A–UMPS axis as a promising therapeutic target against breast cancer, with important translational implications for improving the efficacy of 5-FU for breast cancer patients." (PMID 32382150, 2020). "High SNORD3A transcript and Meis1 and UMPS protein levels predicts a better outcome, but high miR-185-5p level predicts a worse outcome in breast cancer patients receiving 5-FU-based chemotherapy." (PMID 32382150, 2020). "We found that SNORD3A overexpression specifically enhanced the chemosensitivity of breast cancer cells to 5-FU but not to cDDP and PTX." (PMID 32382150, 2020). "SNORD3A expression was also downregulated in breast cancer tissues compared with levels in paired non-cancerous mammary tissues." (PMID 32382150, 2020). "To determine whether SNORD3A enhancement of the sensitivity to 5-FU in breast cancer cells is dependent on UMPS, we stably knocked down UMPS in breast cancer cells with ectopic SNORD3A overexpression." (PMID 32382150, 2020). "Importantly, high SNORD3A transcript and Meis1 and UMPS protein levels predicts a better outcome, but high miR-185-5p level predicts a worse outcome in breast cancer patients receiving 5-FU-based chemotherapy." (PMID 32382150, 2020).
leukemia (3 papers, 2024 to 2025). A malignant (clonal) hematologic disorder, involving hematopoietic stem cells and characterized by the presence of primitive or atypical myeloid or lymphoid cells in the bone marrow and the blood. "Of note, our work revealed novel roles of SNORD118 and SNORD3A as chromatin-association factors that are essential for the maintenance of leukemia cell growth." (PMID 38942785, 2024). "Moreover, in a mouse model that carries the two most prevalent gene mutations in AML, Npm1c and Flt3-ITD, we observed an upregulation of SNORD118 expression as well as the expression of Rnu3b family members (mouse orthologs of human SNORD3A) upon leukemia induction by double mutations (DM)." (PMID 38942785, 2024). "For instance, in leukemia stem cells, SNORD118 and SNORD3A enrich and display a high frequency of trans‐association with chromatin." (PMID 40884233, 2025). "The transcription of SNORD118 and SNORD3A was increased upon leukemia transformation and enriched in leukemia stem cells, but decreased during myeloid differentiation." (PMID 38942785, 2024). "Taken together, these data indicated the importance of SNORD118 and SNORD3A in leukemia maintenance and the potential suitability of SNORD118 as therapeutic vulnerability since healthy hematopoiesis was less affected upon its loss." (PMID 38942785, 2024).
osteosarcoma (3 papers, 2020 to 2024). A usually aggressive malignant bone-forming mesenchymal neoplasm, predominantly affecting adolescents and young adults. "Small nucleolar RNA, C/D box 3A (SNORD3A) was shown to be involved in doxorubicin resistance in human osteosarcoma cells through modulating multiple genes promoting proliferation, ribosome biogenesis, DNA damaging sensing, and DNA repair." (PMID 38033043, 2023). "This trend was not cell line-specific: indeed SNORD3A, SNORA13 and SNORA28 and their respective host genes were progressively up-regulated also in the Dox-resistant variants Saos-2/DX30, Saos-2/DX100 and Saos-2/DX580 derived from Dox-sensitive Saos-2 cells, a second human osteosarcoma cell line." (PMID 32599901, 2020).
acute kidney injury (2 papers, 2024 to 2025). Sudden and sustained deterioration of the kidney function characterized by decreased glomerular filtration rate, increased serum creatinine or oliguria. "This study shows the involvement of Snord3a in acute kidney injury (AKI) by promoting STING‐associated ferroptosis." (PMID 38962954, 2024). "In acute kidney injury, Snord3a is upregulated in renal tubules and drives injury progression by promoting STING-linked ferroptosis; genetic or antisense inhibition of Snord3a alleviates tubular damage in mouse AKI models, nominating snoRNAs as mechanistic targets." (PMID 41300780, 2025).
kidney damage (2 papers, 2024 to 2025). "In this study, we highlight RNA therapy targeting Snord3a ASOs as a promising therapeutic strategy for alleviating ferroptosis and kidney damage in AKI." (PMID 38962954, 2024).
lung carcinoma (2 papers, 2020 to 2024).
prion disease (2 papers, 2013 to 2017). A transmissible disease that is caused by a protein that is able to induce abnormal folding of normal cellular proteins, leading to characteristic spongiform brain changes, which are associated with neuronal loss without an inflammatory response. "Snord3A levels were also elevated in scrapie infected mice, indicating this transcript is not only associated with genetic prion disease but also relates to other etiological prion disease presentations in which misfolded protease resistant PrP is accumulated." (PMID 23349890, 2013). "Moreover Snord3A levels were also elevated in scrapie infected mice, demonstrating Snord3A may be used as a diagnostic tool not only in genetic prion disease, but also in the transmissible prion etiologies." (PMID 23349890, 2013). "Using this strategy, we identified Snord3A, a non-coding RNA transcript, as a marker for prion disease progression." (PMID 23349890, 2013). "Most important, our results indicate that Snord3A expression constitutes a marker not only of genetic prion disease but also for transmissible prions, indicating a common mechanism of action for both conditions." (PMID 23349890, 2013). "In summary, our results indicate that Snord3A may constitute a disease dependent marker for several forms of prion disease." (PMID 23349890, 2013). "We have shown by microarray studies of blood samples from E200K CJD patients and controls that Snord3A may serve as a marker of this genetic prion disease." (PMID 23349890, 2013). "We hypothesize that in addition to its function as a disease marker, Snord3A may play an important role in the mechanism of prion disease manifestation and progression." (PMID 23349890, 2013). "Determining whether elevation of Snord3A expression is specific for prion disease or otherwise also relates to other forms of neurodegeneration will help to decipher its role and mechanism of action in disease." (PMID 23349890, 2013). "To test whether expression of Snord3A constitutes a marker of prion disease etiologies others then genetic, we tested the levels of Snord 3A expression in mice infected with the RML scrapie strain at different ages, as compared to age matched uninfected mice." (PMID 23349890, 2013). "Next, the levels of this transcript were measured in brains of TgMHu2ME199K mice, a line modeling for E200K CJD, and results of these experiments show that Snord3A may serve not only as an indicator of prion disease presence, but also as a marker of disease progression." (PMID 23349890, 2013). "In addition, our results show that if there is a role for the loss of PrPC function in prion disease pathogenesis, it is not mediated by Snord3A." (PMID 23349890, 2013). "To further investigate whether Snord3A expression represents prion disease progression as opposed to general stress, we tested the levels of Snord3A in RNA samples from brains of wt and TgMHu2ME199K mice following administration of copper for 75 days, starting at 3 months of age." (PMID 23349890, 2013).
glaucoma (1 paper, 2023). Increased pressure in the eyeball due to obstruction of the outflow of aqueous humor. "Additionally, SNORD3A, SNORD16, SNORA52, and SNORA23 were differentially expressed in patients with glaucoma." (PMID 37805546, 2023).
ischemia (1 paper, 2024). A hypoperfusion of the BLOOD through an organ or tissue caused by a PATHOLOGIC CONSTRICTION or obstruction of its BLOOD VESSELS, or an absence of BLOOD CIRCULATION. "Moreover, we established cisplatin‐induced and ischemia‐reperfusion injury (IRI)‐induced AKI mice models at different time points to delineate the progressive stages of kidney injury, and Snord3a was significantly elevated in both models." (PMID 38962954, 2024).
Parkinson disease (1 paper, 2013). A progressive degenerative disorder of the central nervous system characterized by loss of dopamine producing neurons in the substantia nigra and the presence of Lewy bodies in the substantia nigra and locus coeruleus. "It will also be important to determine whether levels of Snord3A expression are also elevated in other neurodegenerative diseases such as Alzheimer’s or Parkinson’s disease." (PMID 23349890, 2013).
scrapie (1 paper, 2013). A fatal disease of the nervous system in sheep and goats, characterized by pruritus, debility, and locomotor incoordination. "Snord3A expression was also elevated in scrapie infected mice, but not in PrP0/0 mice, indicating that while the expression levels of this transcript may reflect diverse prion etiologies, they are not related to the loss of PrPC’s function." (PMID 23349890, 2013).
uterine cervix cancer (1 paper, 2020). "SNORD3A and its host genes OSCP1 were found down-regulated in uterine cervix cancer, although the biological and clinical meaning of this change has not been investigated." (PMID 32599901, 2020).
cancer (3 papers, 2020 to 2024). A tumor composed of atypical neoplastic, often pleomorphic cells that invade other tissues. "The 6 up-regulated genes (IL-20, CLK1, SORBS2, ERG1, PIM1, SNORD3A) are involved in cancer development." (PMID 38033043, 2023). "All the most up-regulated genes (IL-20, CLK1, SORBS2, ERG1, PIM1, SNORD3A) are involved in cancer development." (PMID 38033043, 2023). "However, their roles in these cancers were primarily associated with pre-rRNA processing and rRNA maturation, which are well-established functions of SNORD118 and SNORD3A in mammalian cells." (PMID 38942785, 2024). "Top up-regulated genes related to cancer were: (i) IL-20, CLK1, SORBS2, ERG1, PIM1, SNORD3A for normal FHC cells and (ii) TSLP, BHLHA15, LAMP3, ZNF27B, KRT17, ATF3 for cancerous HT29 cells." (PMID 38033043, 2023). "Hence, SNORD3A and SNORD118 do have key functions in maintaining human ribosome biogenesis in cancer cells." (PMID 32111002, 2020). "Nevertheless, both SNORD3A and SNORD118 directly contribute to lung tumorigenesis by promoting ribosome production necessary to maintain cell growth and the high proliferative rate of cancer cells." (PMID 32111002, 2020).
tumor (3 papers, 2020 to 2023). "SNORD3A helps the processing of rRNA and its host gene OSCP1 is a tumor suppressor gene." (PMID 32599901, 2020).
neurodegenerative disease (2 papers, 2013 to 2020). A disorder of the central nervous system characterized by gradual and progressive loss of neural tissue and neurologic function. "In contrast, lipid stress activated the expression of male specific snoRNA, RNU3A (SNORD3A), that is known to be associated with protein misfolding, a key contributor to brain degeneration." (PMID 33142695, 2020). "SNORD3A also reduces resistance to oxidative stress induced lipid peroxidation and hence may worsen stress induced pathological damage in neurodegenerative diseases such as AD." (PMID 33142695, 2020).
immune dysfunction (1 paper, 2022). "The dysregulation of U3 small nucleolar ribonucleoproteins genes (SNORD3B-1, SNORD3A, SNORD3B-2, SNORD3C, and SNORD3D) are related to age-related immune dysfunction, G0/G1 to S phase transition, oxidative-/ER-stress (23349890), and pathogenesis of AD." (PMID 35958988, 2022).
kidney diseases (1 paper, 2024). "Moreover, the human subject study indicated that renal Snord3a concentration negatively correlates with renal function, suggesting the pathological role of Snord3a in kidney disease." (PMID 38962954, 2024).
SNORD3A also shares sentences with these, for which no sentence is quoted: glioblastoma (1 paper); hepatocellular carcinoma (1); liver cancer (1); osteoarthritis (1).